PMF1-BGLAP (PMF1-BGLAP readthrough)
Gene: Protein-coding gene on chromosome 1 (156,212,982 to 156,243,332, forward strand). Ensembl gene ENSG00000260238.
Genetic constraint (gnomAD): Loss-of-function variants: 21 observed, 25.16 expected, observed/expected ratio (o/e) 0.83, 90% interval 0.59 to 1.2. The upper end of that interval is the gene's LOEUF score, 1.2, which puts it in group 5 of 6, group 1 being the genes least tolerant of losing a copy. Missense variants: 253 observed, 252.2 expected, observed/expected ratio (o/e) 1, 90% interval 0.9 to 1.11. Synonymous variants: 96 observed, 101.29 expected, observed/expected ratio (o/e) 0.95, 90% interval 0.8 to 1.12.